RNU6-1078P (RNA, U6 small nuclear 1078, pseudogene)
Gene: Small nuclear RNA gene on chromosome X (71,965,972 to 71,966,074, reverse strand). Ensembl gene ENSG00000201392.
Homologues: Orthologues: chimpanzee U6 (100% identical), macaque U6 (96% identical), dog U6 (88% identical), mouse Gm26441 (86% identical), guinea pig U6 (72% identical). Paralogues in human: RNU6-41P (91% identical), RNU6-1075P (90% identical), RNU6-1122P (90% identical), RNU6-29P (90% identical), RNU6-73P (90% identical), RNU6-1011P (89% identical), RNU6-12P (89% identical), RNU6-13P (89% identical), RNU6-166P (89% identical), RNU6-16P (89% identical), RNU6-252P (89% identical), RNU6-25P (89% identical), and 1285 more.